RELA (RELA proto-oncogene, NF-kB subunit)
Diseases named in the same sentence as RELA in open-access papers (continued):
Sharing a sentence is not in itself a finding about the gene and the disease.
cancer (continued). "In particular, telomerase directly bound to the NF-κB RELA subunit, thus regulating NF-κB-dependent gene expression by binding κB sites in the promoter regions of IL-6 and TNF-α, both critical for inflammation and cancer progression." (PMID 29673141, 2018). "The role of these genes has been reported in cancers, however, networks constructed between TUFT1 and genes had shown that TUFT1 did not associate with these genes except RelA." (PMID 29088838, 2017). "Indeed, ectopic expression of p65/RelA restored hypoxia-induced VEGF promoter activity and secretion after ablation of PKM2 in Capan1 and PaTu2 cancer cells." (PMID 26739387, 2016). "Many other ER+/HER2- cancers expressed no nuclear and little cytoplasm RelA (nNcL); these tumors are perhaps independent of NF-kB influence." (PMID 26460486, 2015). "The mechanisms underlying high NF-κB/relA activity in SCCHN and other human cancer cell types are not clear." (PMID 20716363, 2010). "Conversely, we found no loss of ERBB2, EGFR, ABL1, RELA, and RELB transcript in c-MYC-destabilized cells compared to controls, and the 3′UTRMYC1-18-treated cancer cells tended to restore MYC expression towards the normal female mammary epithelial expression levels." (PMID 39123391, 2024). "The polymeric encapsulated form of curcumin induced anti-cancer activity in breast cancer (MDA-MB-231) and lung cancer (A549) cell lines by modulating the expression of hypoxia-inducing factors (HIF) and the p65 subunit (RelA) of the transcription factor, NF-κB." (PMID 37765192, 2023). "To gather information about p300 and CBP in human cancer, we examined The Cancer Genome Atlas (TCGA) dataset and found significant correlations between EP300 or CBP mRNAs and genes identified by our integrative RNA-seq and ATAC-seq analyses, including RELA, STAT1, NFKB1, IFNGR2, and NLRC5." (PMID 33602823, 2021). "Mechanistically, through repressing NF-κB/RelA and STAT3, PDLIM2 increases expression of genes involved in antigen presentation and T-cell activation while repressing multidrug resistance genes and cancer-related genes, thereby rendering cancer cells vulnerable to immune attacks and therapies." (PMID 31757943, 2019). "However, this induction requires an activated IKK complex, which is not observed consistently throughout many cancer samples, implying the presence of other downstream mechanisms to prolong RelA transcriptional activity." (PMID 31277415, 2019). "Among them were CEBPA and CEBPB (cell cycle regulation), RELA and CREL (NF-κB pathway), TCF7L1 (Wnt/β-catenin signaling pathway), SMAD3 [transforming growth factor beta (TGF-β) signaling], FOXO1 and NFAT, all of which are involved in cancer initiation and progression." (PMID 28344555, 2017). "The nuclear factor kappa enhancer binding protein (NF-κB) families, consisted of P50, P52, RelA (P65), c-Rel, and RelB, have central roles in most, if not all, physiological and pathological processes (e.g., inflammation, immunoregulation, cancer progression and cell survival)." (PMID 29050336, 2017). "Since most research has focused on the functions of components of the classical NF-κB activation pathway, such as P50 and RelA, our findings, along with published functional studies, underscore the necessity of further research into non-canonical NF-κB functions in the various cancer types." (PMID 29371965, 2017). "We showed that the canonical signaling pathway, which is driven by RELA, and the non-canonical pathway, which is driven by RELB, affect cancer cell proliferation and the cancer stem cell maintenance, respectively." (PMID 37175530, 2023).
cancer (continued). "Interestingly, in the group with high RELA expression, patients with cancer with high YAP1 expression had significantly shorter survival times, but not in the group with low RELA expression." (PMID 38164185, 2024). "Consequently, EGFR was lowly expressed in the cancer group versus the normal group in LUAD without a statistical difference (P-value: 0.19) and this expression pattern was similar to ESR1 (P-value: 0.42), MYC (P-value: 0.067), RELA (P-value: 0.058) and SMAD3 (P-value: 0.13)." (PMID 33506873, 2021).
infection (108 papers, 2008 to 2025). The state of being infected such as from the introduction of a foreign agent such as serum, vaccine, antigenic substance or organism. "In future research, we plan to analyze the differential expression of target genes in normal infection models using RT-PCR, including relA, sodA, bipA, and other associated genes." (PMID 40568708, 2025). "Subsequently, we compared the antibacterial activity of polymyxin B against the three stringent response-associated mutants spoT, dksA, and relA to that of the wild-type in a macrophage infection microenvironment." (PMID 35231068, 2022). "To further assess if these transcription factors specifically regulate lfTSLP transcription in hMPV-infected cells, we treated WI-38 cells with siRNAs targeting RelA (which encodes the NF-κB p65 subunit) or IRF3 prior to infection." (PMID 29343779, 2018). "PAO1 ΔrelA/ΔspoT further showed a significant 11.6-fold lower recovery of viable cells (CFU) 3 days post-infection, while the relA-deficient strain as well as the complemented double mutants showed similar bacterial counts, comparable to the wild-type." (PMID 29021784, 2017). "This is the first clinical case showing in vivo development of a mutation in the enterococcal relA gene during prolonged infection that functionally conferred tolerance to clinically relevant antibiotics without a change in clinically tested MIC." (PMID 28049149, 2017). "The relA mutation was first detected 3 days after starting antibiotic therapy and persisted through the clinical course until the infection eventually resolved." (PMID 28049149, 2017). "This relA mutation arose during the course of the infection and persisted throughout the course of therapy despite treatment with antibiotics to which the bacterium retained apparent susceptibility based on MIC testing." (PMID 28049149, 2017). "Infection of J-Lat cell line 6.3 with the RelA-encoding virus caused a 3.5-fold increase in HIV-1 gene expression compared to a control virus that lacks an insert." (PMID 19557157, 2009). "The tracheal colonization advantage of the partial pertactin-deficient strain may be associated with the overexpression of the relA and sodA in vivo infection." (PMID 40568708, 2025). "The tracheal colonization advantage of the partial pertactin-deficient strain BP-L2 may be associated with the overexpression of relA and sodA during in vivo infection." (PMID 40568708, 2025). "The porcine v-rel avian reticuloendotheliosis viral oncogene homolog A (RelA) encoding a p65 kD protein, a major subunit of the NF-kB transcription factor, plays important roles in controlling both innate and adaptive immunity during infection with ASFV." (PMID 38658979, 2024). "While RELA pathogenic variants are sufficient to produce an inflammatory phenotype, the specific features are likely modified by genetic, epigenetic, and environmental factors (such as infection)." (PMID 36926348, 2023). "The (p)ppGpp synthetase activity of RelA enzyme was abolished by point mutations in M. tb, which led to impaired growth and biofilm formation in vitro and abrogates M. tb to persist in the chronic phase of mouse infection." (PMID 34637683, 2021). "Experiments in which ppGpp synthetase activity was supplied to relA spoT mutant strains by providing relA+ or spoT+ alleles in multicopy indicated that the ppGpp required for infection of the host may be synthesized by either RelA or SpoT." (PMID 24575391, 2014). "Timing, signal strength, tissue type, exposure to infections, microbiome, genetic and epigenetic modifiers may influence the phenotypic variation observed in patients with pathogenic mutations in key NF-κB components, including RELA." (PMID 36926348, 2023). "All infections resulted in higher expression levels of the RELA gene, which is related to cytokine production, in comparison with non-infected cells (p < 0.05)." (PMID 40727705, 2025).
infection (continued). "To investigate how L. infantum dampens NLRP3-related inflammatory responses in microglia, we examined the effect of infection on NF-κB p65 (RelA), a central transcription factor crucial for the priming phase of NLRP3 activation." (PMID 41162989, 2025). "During BP-L2 infection in vivo, the relA and sodA genes were significantly overexpressed, which was related to the stringent response and antioxidant stress." (PMID 40568708, 2025). "Upon VSVΔ51 infection, 4-OI inhibited the nuclear translocation of RELA (p65) and reduced the release of IL-6 in the supernatants of virus-infected cells." (PMID 38750019, 2024). "Then, the phosphorylation of transcription factors IRF3 and p65 (RelA), a major component of NF-κB, was measured after the infection." (PMID 39348382, 2024). "Conversely, several IFN-stimulated genes including IFNβ have NF-κB response elements in their promoters, and NF-κB transcription factor RELA activity is required to maintain basal expression level of these genes prior to infection." (PMID 38632238, 2024). "Compared to control RNAi treatments, knockdown of RelA significantly increased VSV-M51R infection as expected." (PMID 38753575, 2024). "RELA targeting slightly increased the plaque size associated with ΔUL26 infection, although these plaques were still substantially smaller than WT HCMV in the RELA targeted cells." (PMID 38768227, 2024). "The RELA protein, a subunit of the NF-KB transcription factor, plays a key role in regulating immune response upon infection." (PMID 38467747, 2024). "In vitro and in vivo experiments involving the infection of bovine macrophages, goat and calf infection model indicated a significant reduction in relA mutant survival compared to wild-type controls." (PMID 37065210, 2023). "During L. braziliensis infection levels of P-p65/RelA and cleaved caspase-3 were increased early at the infection coinciding with the peak of inflammation." (PMID 35145518, 2022). "The expression of IE proteins is associated with inhibition of the phosphorylation of RelA/p65 at Ser536, and the levels of p-Ser536 RelA/p65 are decreased during acute lytic infection of HCMV when IE proteins are expressed." (PMID 35269913, 2022). "In line with this, western blotting showed increased levels of phosphorylated NF-κB p65/RELA starting at 12 h post infection, accompanied by a decrease in IκB levels." (PMID 35022513, 2022). "Studies have shown that RelA protein from M. tuberculosis is essential for its long-term survival under starvation and to establish infection in mice tissues." (PMID 34917044, 2021). "We found collectively among SP-A variants several genes such as AKT1, BTK, CCL9, PPARG, and RELA to exhibit higher expression in females, whereas, CFLAR, C1QC, LSP1, CKAP2, KAT2B, TACC2, and RCC2 exhibited higher expression in males after infection." (PMID 32670284, 2020). "The distinct roles of RelA and SpoT in the infection process and in antibiotic tolerance, and the extent of the (p)ppGpp regulatory network remain to be explored in B. pseudomallei and other pathogenic Burkholderia spp." (PMID 33343543, 2020). "The stationary phase-related genes rpoS, relA, and spoT were upregulated only in the late infection stage (propagation)." (PMID 33255149, 2020). "When E. amylovora tries to colonize plant and starts its infection process, perturbations, such as limited nutrients, acidity, or oxidative stress, activate the RelA/SpoT system and promote (p) ppGpp production." (PMID 32228459, 2020). "paratuberculosis (Map), the causative agent of paratuberculosis (Ptb) in cattle and other species, revealed that deletion of relA, a global gene regulator, abrogates the ability of Map to establish a persistent infection." (PMID 31921129, 2019). "We used FtsZ-GFP fusion to measure the number of dividing cells during infection in the dksA, relA, relA-spoT and recA mutants." (PMID 31725806, 2019).
infection (continued). "Data obtained thus far have shown relA plays a central role in the ability of Map to establish a persistent infection and that deletion of relA leads to immune elimination of the mutant." (PMID 29941017, 2018). "Studies in cattle and goats, however, had shown deletion of one gene, relA, interfered with the capacity of Map to establish a persistent infection, indicating the mutant was a good candidate for further evaluation." (PMID 29941017, 2018). "The observation that the mutation was intermittently identified indicated that both the initial strain and the relA mutant strain coexisted until the later stages of the infection." (PMID 28049149, 2017). "We confirmed this observation by looking at the level of expression of two MeV proteins in the course of infection, MeV-N and MeV-P, which were both more expressed in shp65/RelA-expressing infected cells than in control infected cells." (PMID 28531150, 2017). "Previous studies showed deletion of relA abrogates the capacity of the mutant to establish a persistent infection, allowing immune clearance." (PMID 27764236, 2016). "Cells were treated with rifampin at the time of infection, and RelA phosphorylation assessed at 2, 24, 48, 72, and 96 hpi." (PMID 28066723, 2016). "Combined, these results indicate that infection of THP-1 cells by C. burnetii involves temporal modulation of NF-κB activation via RelA phosphorylation." (PMID 28066723, 2016). "During late infection times (96–144 h), RelA phosphorylation was reduced and de novo C. burnetii protein synthesis did not alter NF-κB activation." (PMID 28066723, 2016). "We found that, consistent with the transient expression experiments, infection of cultured cells with wild-type S. Typhimurium resulted in a marked decreased in the levels of RelA." (PMID 26933955, 2016). "The activation of the canonical transcriptional NF-κB heterodimer RelA/p50 has been widely reported in several infections." (PMID 26400473, 2015). "Taken together, these results suggest that ST-11 isolates promote nuclear cleavage of p65/RelA subunit during late steps of infection." (PMID 26241037, 2015). "Bacterial infection elicited RelA DNA binding activity in IECs that gradually accumulated in the nucleus with substantial contribution from RelA:p52 dimer along with RelA:p50 dimer at day5 post-infection." (PMID 25905673, 2015). "NF-κB subunit p65 (RelA) sustains autocrine IFN-β signaling prior to infection in uninfected cells, and NF-κB and AP-1 subunit c-Jun sustain basal/early IFN-β expression." (PMID 25430775, 2015). "Early after infection, interferons and RelA are induced and appear to cooperate in suppressing the cell-cycle, and altering cellular metabolism." (PMID 26460486, 2015). "The present authors and others have described that infection by L. mexicana or L. amazonensis results in the prompt proteolytic digestion of RelA." (PMID 26400473, 2015). "Differences in RelA expression between poly (I:C) treated tissues and PBMC, likely indicate that populations other than immune cells down-regulate RelA expression in cervical tissues on day 5 after infection." (PMID 26121689, 2015). "We also monitored infected HeLa-G and HeLa-G/ΔN-IκBα cells by immunofluorescence for p65/RelA, the capsid protein p24, and Rex at 48 hours after infection." (PMID 24699669, 2014). "After infection, L. pneumophila ankB mutants prematurely differentiate to the transmissive form, as judged by expression of flaA, relA and spoT, three genes that are induced by starvation in vitro." (PMID 24575391, 2014). "In summary, the present study has provided further data showing deletion of relA abrogates the ability of Map to establish a persistent infection." (PMID 24860792, 2014). "In fact, L. pneumophila relA spoT mutant strains, blocked in ppGpp synthesis, exhibit poor infectivity to macrophages and the bacteria that survive after initial infection are degraded as they are unable to avoid phagosome-lysosome fusion." (PMID 24575391, 2014).